OTUD4 (OTU deubiquitinase 4)
Diseases named in the same sentence as OTUD4 in open-access papers (continued):
Sharing a sentence is not in itself a finding about the gene and the disease.
cancer (12 papers, 2019 to 2026). A tumor composed of atypical neoplastic, often pleomorphic cells that invade other tissues. "Dissecting this unique catalytic mechanism provides a framework for understanding how OTUD4 dysfunction contributes to inflammation-associated cancers such as NSCLC." (PMID 41062071, 2025). "Such work will be critical to connecting OTUD4 dysfunction to cancer progression and to informing therapeutic strategies." (PMID 41062071, 2025). "Research confirmed that OTUD4 is a potential predictor of several human cancers and is also involved in DNA alkylation damage repair, which is important in cancer radiation and chemotherapy." (PMID 38429268, 2024). "Ovarian tumor family deubiquitinase 4 (OTUD4), a member of the OTU deubiquitinating enzyme, is implicated to decrease in cancer to regulate cell apoptosis." (PMID 37726265, 2023). "This suggests that while OTUD4 alters TGFβ signalling in the majority of cancers it only positively correlates with EMT in a relatively minority cancers highlighting the tissue specificity of OTUD4 and EMT in cancer plasticity." (PMID 32973272, 2020). "As TGFβ is a major regulator of epithelial-mesenchymal transition (EMT) we sought to determine if OTUD4 regulates EMT in cancer." (PMID 32973272, 2020). "We have provided evidence of OTUD4′s ability to regulate the TGFβ pathway in cancer and in certain contexts influences EMT." (PMID 32973272, 2020). "The combination of ST80 with anti–PD-L1 therapy shows promise in preclinical models, however, the potential synergistic effects of ST80 with other immunotherapeutic agents, conventional chemotherapy, and the impact of OTUD4/CD73 axis blockade in other cancers remain to be explored." (PMID 38747288, 2024). "In addition, alkylation damage which is critical for cancer chemotherapy can also be regulated by OTUD4." (PMID 35109842, 2022). "Next, we sought to determine if OTUD4 expression correlated with TGFβ signalling in cancer." (PMID 32973272, 2020). "Interestingly, when the TCGA pan-cancer dataset was analyzed as a whole, OTUD4 expression negatively correlated with the generic EMT signature." (PMID 32973272, 2020). "However, its involvement in cancer remains unclear, and research specifically investigating the role of OTUD4 in cancer immunology is limited." (PMID 38747288, 2024). "Notably, OTUD4 overexpression heightened levels of membrane-bound CD73 in cancer cells." (PMID 38747288, 2024). "Ultimately, the identification of OTUD4 adds greater resolution to our knowledge surrounding the cell’s ability to regulate the TGFβ pathway and defines OTUD4 as a biomarker for TGFβ activity, with its expression acting in proxy to reveal the intrinsic activity of this cancer-relevant pathway." (PMID 32973272, 2020). "However, whether OTUD4 participates in DSBs repair, especially HR, and modulates radiosensitivity of cancer cells remain to be elucidated." (PMID 31011293, 2019). "In this review, we comprehensively summarize the roles of seven DUBs with OTU structural domains in cancer progression and antiviral immune responses, including OTUD1, OTUD2, OTUD3, OTUD4, OTUD5, OTUD6A, and OTUD6B." (PMID 41050073, 2025). "Hence, OTUD4 could be a potential target for cancer therapy via regulating DNA damage repair." (PMID 31011293, 2019). "On the contrary, high expression of OTUD4, OTUD5, and TNFAIP3 could enhance the sensitivity of cancer cells to radiotherapy." (PMID 40469292, 2025).
infection (5 papers, 2011 to 2025). The state of being infected such as from the introduction of a foreign agent such as serum, vaccine, antigenic substance or organism. "The increases in OTUD4 protein levels correlated with similar increases in its mRNA levels indicating stimulation of Otud4 gene transcription during infection." (PMID 35516420, 2022). "To test this, we first transfected Neuro-2a cells with an IFN-β promoter luciferase reporter construct together with a plasmid expressing OTUD4 or VIM before infection at an MOI of 2 for 16 h." (PMID 35516420, 2022). "Additionally, OTUD4-deficient mice exhibited less inflammation and immune cell infiltration in the lungs after MHV68 infection compared to control mice." (PMID 40208866, 2025). "Although the functions of OTUD4 in multiple biological processes including innate immune response have been investigated, it is unclear whether and how OTUD4 regulates intestinal inflammation and infection." (PMID 37193092, 2023). "Unexpectedly, OTUD4 also increased luciferase activity during mock infection suggesting that OTUD4 could raise the baseline expression of IFN-β in unstimulated cells." (PMID 35516420, 2022). "The down-regulated miR-29b and miR-29a are both or each connected to up-regulated SMARCE1, HBO1, NKX6-1, HOXA10, HBP1, OTUD4, that could be further considered as potent targets during infection." (PMID 21408164, 2011). "To investigate OTUD4’s role in MHV68 replication in vivo, we administered tamoxifen to Otud4fl/fl Cre-ERT2+/- and Otud4fl/fl Cre-ERT2-/- mice to induce OTUD4 knockout, followed by MHV68 infection via intranasal inoculation." (PMID 40208866, 2025). "Then, we generated primary mouse lung fibroblasts (MLFs) from these mice, and induced OTUD4 knockout with 4-hydroxytamoxifen and then performed MHV68 infection ex vivo." (PMID 40208866, 2025). "Among these, one group containing OTUB1, OTUB2, OTUD4, OTUD5, OTUD6B, and OTUD7B showed obvious upregulation 6 h post-infection, followed by downregulation 12 h post-infection." (PMID 37650650, 2023). "To explore whether OTUD4 has a critical role in herpesvirus replication in vivo, we turned to MHV68 for in vivo infection studies in mice, since KSHV exhibits strict host tropism and primarily infects humans as the only natural host." (PMID 40208866, 2025). "Overexpressed OTUD4 enhanced type I interferon expression during infection with the ICP0-null but not wild-type virus." (PMID 35516420, 2022).
neurodegenerative disease (3 papers, 2019 to 2023). A disorder of the central nervous system characterized by gradual and progressive loss of neural tissue and neurologic function. "We will now discuss how our work changes the perspective on OTUD4 with respect to stress granule formation, granule transport in neurons, (local) translation and regarding its potential role in neurodegenerative diseases." (PMID 31138677, 2019).
bacterial infection (1 paper, 2023). "Taken together, these results suggest that OTUD4 negatively regulates K63-linked ubiquitination of MyD88 and MyD88-dependent activation of NF-κB and MAPKs, thereby restricting the expression of AMPs in IECs and promoting bacterial infection and inflammation in the gut." (PMID 37193092, 2023). "We further show that OTUD4 negatively regulates the expression of AMPs in IECs after DSS treatment or bacterial infection in a MyD88-dependent manner." (PMID 37193092, 2023). "Higher concentrations of DSS cause more severe epithelial damage and bacterial infections in the intestine, which would induce more robust TLR-MyD88 signaling that reciprocally triggers regulatory machinery by OTUD4." (PMID 37193092, 2023). "Taken together, our results indicate that OTUD4 in IECs promotes bacterial infection by inhibiting the expression of AMPs." (PMID 37193092, 2023). "Here in this study, we have demonstrated that OTUD4 inhibits the expression of AMPs in Paneth cells and supports intestinal inflammation and bacterial infection through deubiquitinating MyD88." (PMID 37193092, 2023). "The bacterial counts in feces, cecum, liver and spleen of the Vil-Cre;Otud4fl/fl mice were also significantly reduced compared to Otud4fl/fl mice, indicating that OTUD4 promotes bacterial infection in vivo." (PMID 37193092, 2023). "Collectively, these data demonstrate that OTUD4 in Paneth cells negatively regulates the expression of AMPs and promotes intestinal inflammation and bacterial infection." (PMID 37193092, 2023). "Consistently, we found that knockout of OTUD4 in IECs increased the phosphorylation of TAK1, p65 and p38 after DSS treatment or S.t. infection, indicating that OTUD4 restricts the activation of NF-κB and MAPKs in IECs during gut inflammation or bacterial infection." (PMID 37193092, 2023).
OTUD4 also shares sentences with these, for which no sentence is quoted: hypogonadotropic hypogonadism (4 papers); liver cancer (2); ovarian carcinoma (2); breast tumors (1); cerebellar ataxia (1); colorectal cancer (1); Crohn disease (1); depression (1); diffuse large B-cell lymphoma (1); Follicular Cyst (1); frontotemporal lobar degeneration (1); head and neck squamous cell carcinoma (1); Hypodontia (1); intrahepatic cholangiocarcinoma (1); liver diseases (1); microphthalmia (1); myocardial infarction (1); pancreatic cancer (1); pancreatic ductal adenocarcinoma (1); squamous cell carcinoma (1).